ENSG00000256349 (novel protein)
Gene: Protein-coding gene on chromosome 11 (66,509,079 to 66,533,613, forward strand). Ensembl gene ENSG00000256349.
Genetic constraint (gnomAD): Loss-of-function variants: 61 observed, 77.18 expected, observed/expected ratio (o/e) 0.79, 90% interval 0.64 to 0.98. Missense variants: 738 observed, 834.38 expected, observed/expected ratio (o/e) 0.88, 90% interval 0.83 to 0.94. Synonymous variants: 286 observed, 336.87 expected, observed/expected ratio (o/e) 0.85, 90% interval 0.77 to 0.94.